BRCA1 (BRCA1 DNA repair associated)
Diseases named in the same sentence as BRCA1 in open-access papers (continued):
Sharing a sentence is not in itself a finding about the gene and the disease.
cancer (continued). "While the combination of PARPi with immunotherapy holds potential for BRCA1/2‐mutant cancers, limited benefits have been reported in recent studies, highlighting the need for alternative strategies to potentiate antitumor immunity and immunotherapy response." (PMID 39412086, 2024). "This would induce synthetic lethality in human cancers with HDR gene deficiency, e.g. BRCA1/2 mutations, as well as sensitize cancer cells to PARPis." (PMID 38714348, 2024). "BRCA1 pathogenic variants, enriched in basal-like/TNBC, and the epigenetic silencing of BRCA1, which impairs DNA repair, play significant roles in cancer progression." (PMID 39484719, 2024). "Because PARP-DNA complexes lead to the formation of DSBs with bulky PARP proteins upon fork collision, cancer cells engage multiple repair factors beyond BRCA1/2 to manage PARP-trapping." (PMID 38961202, 2024). "Some PARPi treatment approvals are limited to cancers that have gPVs in BRCA1/2 or genomic instability features indicative of HRD." (PMID 38848470, 2024). "In this context, the tumor suppressor gene BRCA1 has been shown to be increased in response to natural compounds exhibiting anti-cancer activities such as liquiritigenin and genistein." (PMID 38257347, 2024). "Secondary mutations in BRCA1 and 2 genes have been described as one of the mechanisms of cisplatin resistance in BRCA-mutated cancers." (PMID 38474294, 2024). "Deficiency in DSB repair mediated by BRCA1 and BRCA2 can lead to the proliferation of cancer cells due to the accumulation of driver mutations." (PMID 38666816, 2024). "Promoters’ analysis highlighted enriched transcription factor binding sites for developmental genes, such as HOX and SOX family genes (HOXB13 and SOX10), and for well-known cancer-related genes, like BRCA1." (PMID 38891761, 2024). "The tumor suppressor genes breast cancer 1 (BRCA1) and breast cancer 2 (BRCA2) maintain cellular genome integrity through various processes, including homologous recombination (HR)-mediated repair of DNA breaks." (PMID 38956205, 2024). "No specific threshold was introduced for testing for HBOC until the 2004 NICE guideline which set a 20% threshold for likelihood of BRCA1/2 and only recommending testing in people affected with a relevant cancer to identify index cases for testing relatives." (PMID 38478259, 2024). "This is crucial for identifying all patients with BRCA1/2 TPVs to provide high-quality care, as well as for guiding genetic cascade testing to ultimately prevent cancer in unaffected relatives with BRCA1/2 GPVs." (PMID 38730634, 2024). "CX-5461, also known as pidnarulex, is a strong G4 stabilizer and has received FDA fast-track designation for BRCA1- and BRCA2- mutated cancers." (PMID 39027314, 2024). "The development of PARP inhibitors like Olaparib has significantly improved the treatment of cancers with DDR defects (e.g., BRCA1 or BRCA2 mutations) based on synthetic lethality." (PMID 39372203, 2024).
cancer (continued). "Gene-level analysis of variant prevalence revealed no significant enrichment of PLP variants in specific genes when comparing the healthy individuals (4 for BRCA1, 6 for BRCA2) and cancer patients (8 for BRCA1, 12 for BRCA2) (Fisher’s Exact P = 0.745)." (PMID 38566028, 2024). "The chemotherapeutic agent CX-5461, or pidnarulex, has been fast-tracked by the United States Food and Drug Administration for early-stage clinical studies of BRCA1-, BRCA2- and PALB2-mutated cancers." (PMID 38036782, 2024). "In contrast to the aggregation of PLP variants within the functional domains of BRCA (BRCA2 BRC repeat and DNA-binding) in cancer patients, we observed a uniformed distribution of PLPs across BRCA1 and BRCA2 sequence in the healthy individuals." (PMID 38566028, 2024). "We show that BRCA1 and BRCA2 mutation statuses differentially impact the regulation of the Wnt/β-catenin signaling pathway, a major effector of cancer initiation and progression." (PMID 39028933, 2024). "Genetic testing of the BRCA1 and BRCA2 gene mutations is particularly recommended for individuals with familial susceptibility to cancer or who have a personal history of cancer." (PMID 38785549, 2024). "The single PPTP/C pediatric model (KT-10) with a homologous recombination deficiency (HRD) mirrors the clinical setting in which genetic loss of BRCA1/2, BARD1, PALB2, and other genes associated with HRD is uncommon in pediatric cancers." (PMID 39510293, 2024). "Utilizing unstimulated NK cells minimizes bias when describing a baseline functional profile in healthy women (devoid of a clinically confirmed cancer), demonstrating superiority over BRCA1-deleted murine models." (PMID 38539519, 2024). "From the Cancer Genome Atlas (TCGA), we also retrieved the LST and tAI counts of cancers from individuals who are heterozygous for CHEK2 gPVs or BRCA1/2 gPVs." (PMID 38848470, 2024). "We further confirmed that POLAi-induced ssDNA gaps and cellular sensitivity to POLAi depend on BRCA1 loss using the GFP- and BRCA1-reconstituted MDA-MB-436 cancer cell lines." (PMID 39191785, 2024). "Prior publications have shown that PARP inhibition promoted synthetic lethality in BRCA1/2 mutant cancers via inhibition of single strand break repair and base excision repair pathways." (PMID 38542143, 2024). "BRCA1 and BRCA2 stand out as the predominant genes associated with this specific cancer type compared to others." (PMID 38672725, 2024). "One primary pathway involves secondary or “reversion” mutations in BRCA1 or BRCA2 genes that restore the functional reading frame, thereby reinstating homologous recombination repair capabilities in cancer cells." (PMID 39272683, 2024). "The use of readily available historic data from national cancer registries may offer a new method for determining family history of young adult females and improve current gaps in BC/OC prevention and more efficient identification of pathogenic variants BRCA1/2 mutation female carriers." (PMID 39124739, 2024). "Collectively, these data highlight BRCA1 as a potentially pivotal determinant in the anti-cancer efficacy of BI-2536." (PMID 39085197, 2024). "Wnt signaling was likewise differentially regulated when 4T1 BRCA2-null and 4T1 BRCA1-null cancer cells were compared (P = 0.013)." (PMID 39028933, 2024). "We previously demonstrated that the levels and arrangements of CpG island methylation at the BRCA1 promoters in WBCs are comparable among cancer patients, newborns, and adult BRCA1 methylation carriers." (PMID 38542081, 2024). "The Cancer Genome Atlas shows that approximately 50% of HGSC patients have HRD, including germline and somatic BRCA1/2 mutation in 11–15% and 7% of women, respectively." (PMID 38409030, 2024).
cancer (continued). "By dissecting the functional impact of BRCA1 VUS on splicing, our work contributes to the interpretation of variants relevant to cancer risk and prevention strategies and expands the knowledge of BRCA1 genetics in northern Africa." (PMID 38786046, 2024). "We identified a consistent correlation between BRCA1 methylation and genomic biomarkers for HRD across all cancer types with BRCA1 methylation." (PMID 39055334, 2024). "Hypermethylation of cancer suppressor genes such as RB1, CDKN2A, MLH1, VHL, and BRCA1, leading to their repression, has been observed in various cancer types." (PMID 38970307, 2024). "Our analysis suggests that undergoing both RRSO and RRM is the most effective and cost-effective option for BRCA1, BRCA2, and PALB2 PV carriers, with younger surgery ages for those with higher cancer risk preventing more cancers." (PMID 38334999, 2024). "We gathered 352 distinct germline variants (127 for BRCA1 and 225 for BRCA2) from 2,080 Han Chinese healthy individuals and 522 patients with BRCA mutation-related cancer." (PMID 38566028, 2024). "In contrast, other DNA damage response and repair genes, including BRCA1, BRCA2, ATM, BRIP, POLQ, and CDK12, were significantly more often mutated in CDX2-suppressed cancers." (PMID 39452477, 2024). "In conclusion, this pan-cancer study broadens our understanding of BRCA1 and RAD51C methylation and identifies important avenues for further exploration, especially due to significant therapeutic implications." (PMID 39055334, 2024). "In vitro study suggested that 6-G possesses anti-cancer activity by inducing cell apoptosis in human PCa PC-3 cells by affecting AR regulated DDR genes (BRCA1, BRCA2, and ATM ) which is involved in cell survival." (PMID 38166796, 2024). "In summary, the inhibitory effect of AIL on BRCA1 made cancers with normal BRCA1 function sensitive to OLP's PARP inhibition when they are used together." (PMID 38009603, 2024). "Resultantly, NHS England Cancer Programme introduced clinical implementation of population-based BRCA1 and BRCA2 testing for all UK Jewish adults in January 2024." (PMID 39001386, 2024). "This study proves that the inhibitory effect of AIL on BRCA1 allowed even cancer cells with normal BRCA1 function to be sensitive to PARP inhibitors when it is simultaneously administered with OLP." (PMID 38009603, 2024). "Curcumin, a substance with demethylating capabilities and the capacity to improve antitumor immunity, has promise as a cancer preventative agent, particularly for BRCA1-methylation carriers." (PMID 38542081, 2024). "Many susceptibility genes, notably BRCA1, BRCA2, and the mismatch repair genes, are associated with multiple types of cancer, 2 but in general, cancer pleiotropy is poorly understood." (PMID 39209703, 2024). "Promoter-associated DNA CpG methylation has been reported in cancer for some HRR genes, specifically, BRCA1 and RAD51C." (PMID 39055334, 2024). "One of the applications of NGS is inherited cancer testing by targeted NGS panels focusing on high‐penetrant/high‐risk mutated genes, such as BRCA1 and BRCA2." (PMID 37092543, 2023). "PARPi are particularly active in cancer cells with alterations in HRR, such as BRCA1 or BRCA2 pathogenic mutations, through the well-known mechanism of “synthetic lethality”." (PMID 37842243, 2023). "Cancer cells containing mutant BRCA1 were also determined to suppress glycolysis by repressing the genes GLUT1, HK1, HK2, and LDHA." (PMID 37110218, 2023).
cancer (continued). "It is noteworthy that cells and organisms survive with mutations in ATM or other components required for HRR, such as BRCA1 and BRCA2, but at the expense of genomic instability and cancer predisposition." (PMID 37627523, 2023). "BRCA1 and BRCA2 proteins are well-known HR-mediated repair regulators, and loss of BRCA1/2 function leads to compromised HR-mediated repair capacity in cancer cells, so cells presenting this phenotype are highly sensitive to PARP inhibitor treatment." (PMID 37415733, 2023). "Women who are subsequently found to carry a BRCA1/2 PV engage in complex preventive decision making to address their individual cancer risks." (PMID 36767056, 2023). "Recently, the UHRF1/BRCA1 DNA repair complex was shown to constitute an interesting target to treat cancer as it sensitizes the cells to DNA damage by giving them less opportunity to initiate DNA repair." (PMID 37630248, 2023). "For cancer-free AJ women the probability of having a pathogenic mutation in CHEK2 is 1.4%–1.7% and the chance for a mutation in BRCA1 or BRCA2 is less than 2.5%." (PMID 36845387, 2023). "The fact that curcumin is a suppressor of miR-155 in tumor cells and a restorer of IL2RG in blood cells holds the potential to be an effective preventive therapy against cancer formation in BRCA1-metylation carriers." (PMID 37240365, 2023). "For OV and many other types of cancer, dysfunction of DDR and subsequential enhancement of genomic instability, i.e., BRCA1/2 gene mutation induced DDR deficiency, is a key etiology of tumorigenesis." (PMID 38136595, 2023). "BRCA1/2 are crucial for homologous recombination (HR) during DSB repair, and pathogenic variants are linked to genome instability and the progression of cancer." (PMID 36865806, 2023). "Extending clinical genetic screening from BRCA1 and BRCA2 to 13 established cancer predisposition genes almost doubles the diagnostic yield, which has implications for genetic counseling and clinical guidelines." (PMID 37563628, 2023). "Restoration of HR repair capacity in BRCA1/2 mutant cancer cells due to the disruption of DNA end-resection blockers such as 53BP1 and RIF1; ii." (PMID 37415733, 2023). "Breast cancer type 1 susceptibility protein (BRCA1) is another oncosuppressive protein, which, upon LOF mutations, is associated with an increased risk of developing different types of cancer." (PMID 37190033, 2023). "RAD50, part of the MREll complex, influences the predisposition to cancer due to its complex interactions with various oncogenes such as ATM, BRCA1, and CHK2." (PMID 38213474, 2023). "When BRCA1 is lost, uncontrollable accumulation of stem cells occurs, and finally, a small number of stem cells missing BRCA1 develop into cancer." (PMID 36632469, 2023). "Since BRCA1 is important for initiating end resection in normal cells, BRCA1-mutant cancer cells use EEPD1 to cleave stressed replication forks and initiate end resection during RAD52-mediated HR repair of stressed replication forks." (PMID 36683914, 2023). "We note with interest the diversity of BRCA1 and BRCA2 variants within our cancer patient group, and the enrichment of BRCA2 VUS in cancer patients." (PMID 37306523, 2023). "Mouse models, in particular, have played a pivotal role in showing the contributions of BRCA1 to cancer." (PMID 37762577, 2023). "The present study addresses a gap in the literature by investigating coping self-efficacy and its relationship with psychological and decision-related outcomes after genetic test result disclosure in cancer-unaffected female BRCA1/2 PV carriers." (PMID 36767056, 2023).
cancer (continued). "During DNA replication, UHRF1 accumulates at DSBs through its interaction with the BRCT (BRCA1 C-terminal) domain of BRCA1 (breast cancer gene 1) and phosphorylation of UHRF1 at Ser 674 by CDK2/cyclin." (PMID 37630248, 2023). "In summary, we discussed various aspects of R-loops in cancer, specifically focusing on their interplay with DNA repair proteins such as BRCA1, BRCA2, and ATR." (PMID 37108225, 2023). "Malignant tumor cells are susceptible to the occurrence of mutations in the BRCA gene, such as the existence of mutations in the BRCA1/2 gene in patients with TNBC." (PMID 37641116, 2023). "Analysis of high-risk cancer pedigrees identified in this powerful Utah resource previously provided the identification of BRCA1 and BRCA2, and CDKN2A, which remain the most common cancer predisposition genes to be identified." (PMID 37046747, 2023). "To evaluate the use of WBC miR-155-5p as a molecular biomarker for the assessment of cancer risk in CF-BRCA1 methylation-carrying females, we measured the level of WBC miR-155-5p in ten BRCA1-methylation carriers, as used in our previous study." (PMID 37240365, 2023). "Each of these cases also carried other germline mutations (PBRM1, C7 and MYH9, BRCA1, ANKRD26) of which BRCA1 and ANKRD26 are cancer predisposition genes." (PMID 37869077, 2023). "After excluding patients who underwent chemotherapy or surgery before the ultrasound, we evaluated 89 cancers in BRCA1-positive and 83 in BRCA2-positive patients." (PMID 36905492, 2023). "Accurate age-dependent estimates of cancer penetrance in BRCA1 PV carriers are crucial in genetic counseling to make informed decisions about preventive measures that correspond to personalized BC or OC risk." (PMID 37296919, 2023). "Despite this, most triple-negative breast cancers (80%) express markers of basal-associated cancer, including basal cytokeratin, vimentin, EGFR, and mutated BRCA1/2." (PMID 37513983, 2023). "The last cluster presents strong ‘two-hit’ preferences in a pan-cancer analysis as well as in single cancer types and includes two classical CPGs (BRCA1 and BRCA2) and 19 OMIM genes." (PMID 38143269, 2023). "The combination was also assessed in a Phase 1 trial enrolling patients with BRCA1/2, HRD-altered, and/or PI3KCA-mutated cancers; 14 (25%) patients achieved a partial response and the combination was safe." (PMID 37430137, 2023). "BRCA1 is predominantly acknowledged for its pivotal role in DNA repair and its significant contribution to cancer prevention." (PMID 37762577, 2023). "We suggest that these functional determinations of BRCA1 variants can be used to augment the information that clinical cancer geneticists provide to patients who have a VUS in BRCA1." (PMID 37578980, 2023). "We recently investigated R-loop resolution in BRCA1-mutant cancer cells and found that these cells repress many microRNAs (miRs), probably due to overexpression of IRE1 RNase which degrades miRs involved in tumor suppression." (PMID 38069223, 2023). "In previous literature kaempferol, aglycone flavonoid, showed bad affinity for BRCA-1 genes with score -3.661 kcal/mol but reported to have anticancer potential in breast & many other cancers." (PMID 37925393, 2023). "siRNA-mediated APE2 knockdown leads to substantially more γ-H2AX and micronuclei in pancreatic cancer cell PANC1 under unperturbed conditions, suggesting that inhibiting APE2 increased DNA damage in BRCA1/2-proficient cancer cells." (PMID 36755963, 2023). "During follow-up, subsequent cancers were more frequently diagnosed in BRCA patients (19.0% in BRCA1 vs. 21.0% in BRCA2 vs. 5.9% in BRCA-wt, p = 0.002)." (PMID 38067403, 2023). "The common pathway of DNA damage sensing and cell replication control is shared with other proteins, such as BRCA1, PLAB2, BRCA2, and RAD51, whose genes are implied in cancer susceptibility conditions." (PMID 37509701, 2023).